IL6 (interleukin 6)
Diseases named in the same sentence as IL6 in open-access papers (continued):
Sharing a sentence is not in itself a finding about the gene and the disease.
tumor (continued). "Production of VEGF by RMG-1 cells was only mildly suppressed by anti-IL-6 antibody treatment as evidenced by ELISA analysis of culture supernatant, whereas osteopontin production by RMG-1 tumor cells was significantly suppressed by anti-IL-6 (p < 0.01)." (PMID 33833265, 2021). "First, using specific sensitive ELISA, we validated that IL-6 plasma levels are elevated in tumor-free mice treated with anti-PD1 and anti-CTLA-4 antibodies." (PMID 33707313, 2021). "To directly evaluate the correlation between the lncRNA MIAT/HMGB1/IL6 axis and tumor resistance in NPC patients, we collected samples from cisplatin-sensitive patients and the patients developed resistance." (PMID 34094941, 2021). "miR-155 was previously shown to regulate inflammatory cytokine production (IL-6, IL-10 and TNFα) in tumor-activated macrophages via targeting CEBPB." (PMID 33540559, 2021). "Our findings indicate significant upregulation of the examined interleukins (IL-1β, IL-6 and IL-17) in the surgical margin in comparison to the tumour lesion." (PMID 33658555, 2021). "TGF-β1 and IL-6 are crucial cytokines for Th17 differentiation and are upregulated in the tumor tissue of patients with CRC." (PMID 34394377, 2021). "Recent evidence suggests that IL-6 is a central player linking chronic inflammation to cancer by driving tumour initiation and subsequent growth and metastasis." (PMID 33654093, 2021). "IL-6 is a cytokine that have extensive effects and its overexpression has been reported in almost all kinds of tumours." (PMID 34393797, 2021). "IL-6 and IL-8 are inflammatory cytokines that are produced and secreted by various cells types, including immune cells and tumor cells." (PMID 34680349, 2021). "In NSCLC cells, IL-6 neutralizing antibodies have been shown to inhibit tumor growth in mouse transplanted tumor models by inhibiting JAK1/STAT3 signaling." (PMID 34079469, 2021). "If analyzed by tumor size, patients with a tumor diameter from a 4 to 7 cm IL-6 level predicted survival by Kaplan–Meier analysis (p = 0.001)." (PMID 32621022, 2021). "It has been shown that CAF-derived IL-6 can also regulate the expression of osteopontin (OPN) in tumor cells, as OPN promotes invasion of head and neck cancer cells." (PMID 34572947, 2021). "It was also shown that tumor cells alone can modulate the gene expression profile of naïve MSCs, including IL-6, BST2, ADAMTS12, MX2, LOXL2 and GREM1." (PMID 34513701, 2021). "As a rule, most proinflammatory cytokines including tumor necrosis factor α (TNF-α), interleukin 6 (IL-6) and interleukin 17 (IL-17), produced by either the host immune system or the tumor cells themselves, promote tumor progression." (PMID 34367064, 2021). "In inflammatory immune cells such as macrophages and neutrophils, the activation of NF‐κB activates the expression of inflammatory cytokines such as TNFα, IL‐1β, and IL‐6, thereby promoting the proliferation of malignant cells and tumor stromal cells." (PMID 34977871, 2021). "Inflammatory TME is regulated by several cytokines, including interleukin (IL)-1 and IL-6, which promote cancer cell proliferation and invasion, increasing intracellular signaling by NF-kB, and cytokine receptor activation accelerates tumor progression." (PMID 35010954, 2021). "We also evaluated T cells in the thymi of pre-tumor mice since IL-6 is known to promote T cell differentiation." (PMID 33651821, 2021). "Although we did not measure IL-6 secreted by SASP-positive cells, we think that high sTIL density and high iCD103 + lymphocyte levels in SASP-positive tumors would be, in part, T cell migration to tumor site by IL-6 signaling by senescent cells." (PMID 34267603, 2021). "It has been reported that IL-6 promotes the polarization of monocytes recruited by tumor cells into TAM and the amplification of MDSCs in tumor microenvironment, IL-17 enhanced the expression of PD-1 and HAVCR2 in tumor-infiltrated CD8+ T cells." (PMID 33679751, 2021).
tumor (continued). "Studies have shown that in the tumor microenvironment, the adhesion of tumor cells to stromal cells can promote stromal cells to secrete high levels of IL-6, tumor necrosis factor-α, and osteopontin as ligands of integrins to bind and activate integrins." (PMID 34295898, 2021). "Interleukin-6 (IL-6) is produced by fibroblasts, monocytes/macrophages, T lymphocytes, B lymphocytes, epithelial cells, and a variety of tumor cells." (PMID 34367136, 2021). "Neurotransmitter substance P (SP) (a member of the tachykinin neuropeptide family), secreted by both tumor and stromal cells, is known to induce many cytokines (IL-1, IL-6, TNF-α)." (PMID 33925575, 2021). "IL-6 is a pleotropic cytokine with complex and varying impacts on tumor growth and anti-tumor immunity." (PMID 33922465, 2021). "Using loss-of-function experiments, we showed that the inflammatory response triggered by IL-6 facilitated cancer cell stemness and tumor progression in an m6A-IGF2BP2-dependent manner in CCA patients." (PMID 34347395, 2021). "On the other hand, as antitumor effectors, MCs produce mediators (e.g., tryptase, chondroitin sulfate, TNF, IL-1 and IL-6) that increase antitumor inflammatory reactions, inducing tumor apoptosis and decreasing the invasiveness of cancer cells." (PMID 34635121, 2021). "IL-6 and IL-8, encoded by the IL6 and CXCL8 genes respectively, are key cytokines involved in tumour growth, angiogenesis and metastasis." (PMID 34445479, 2021). "Tumor-associated macrophages loaded with iron can promote the production of ROS and pro-inflammatory cytokines (tumor necrosis factor-α and interleukin-6), thereby inducing tumor cell death in lung cancer." (PMID 34804126, 2021). "IL-6, secreted by CAFs, binds to its cognate receptor expressed by tumor cells and promotes their growth and the acquisition of an invasive phenotype by activating the IL-6–JAK–STAT axis and the notch pathway." (PMID 34360868, 2021). "Although correlation with other clinical factors or tumour characteristics was not identified, the analysis was limited by the heterogeneity across studies in the different sources for IL6 detection (tumour vs. serum)." (PMID 34834425, 2021). "For example, tumor-derived exosomes modified with specific ncRNAs can target IL-6, IL-17, IL-1B, TGFβ, IFN-γ, and TLR4 to induce dendritic cell maturation and to enhance its immune-stimulating capacity." (PMID 34692482, 2021). "CRC cells can themselves increase the secretion of IL-6 from fibroblasts, which in turn induces invasion and expression of the integrin β6 adhesion molecule (an indicator of tumor progression) in CRC cells." (PMID 33557173, 2021). "Hepcidin gene expression correlated with BMP6 and IL6 expression, as well as tumor-infiltrating anti-cancer immune cell populations." (PMID 34277457, 2021). "MMP-9, similar to IL-6, is produced by various tumor cells and inflammatory cells—neutrophils, eosinophils, monocytes, lymphocytes, and alveolar macrophages." (PMID 34439874, 2021). "The effective dose of DIM reversed the upregulation of the expression of CCL-2, IL-6, and IL-8 in GC-MSCs by β-TrCP-mediated iκBα degradation and NFκB signaling pathway activation, thereby enhancing tumor progression." (PMID 33842314, 2021). "We made cachexia avatars using PDXs, tested the centrality of IL-6 by deleting it from tumor cells, and modeled the resulting effects and deduced tissue crosstalk in fat and muscle using cell culture." (PMID 33851955, 2021). "On the other hand, knockdown of EEF1A2 decreased the expression of IL-6 which is considered to play key roles in tumor immune evasion." (PMID 34446611, 2021). "IL‐6 secreted by tumor cells can activate the signal transducers and activators of transcription 3 (STAT3)‐VEGF pathway of lymphatic endothelial cells and encourage lymphatic metastasis of the tumor." (PMID 34977870, 2021).
tumor (continued). "The present study confirmed the profound increase in pro-inflammatory markers (Il6, Il1β, and Ptgs2) in tumor compared to peri-tumoral tissue in mice of all genotypes." (PMID 34526660, 2021). "In summary, this study provides the first evidence that miR-148b-5p acts as a tumor suppressor miRNA, and that miR-148b-5p deficiency induces GC development and immune tolerance via the miR-148b-5p/ATPIF1/TNFa plus IL6 and CSF1 axis." (PMID 33717068, 2021). "For example, senescent cells, which accumulate as a result of aging, secrete tumor-promoting inflammatory proteins, the so-called senescence-associated secretory phenotype (SASP) factors, which include IL-6 and IL-8." (PMID 34063828, 2021). "In general, CAFs secrete major cytokines including TGF-β1, C-X-C motif chemokine ligand 12 (CXCL12), platelet-derived growth factor (PDGF) and interleukin-6 (IL-6) which promote tumor growth and metastasis." (PMID 34638283, 2021). "Meanwhile, tumor infiltrating immune cells secreted IL-6 is able to stimulate IL-6/STAT3 signaling pathway to promote the malignant behaviors of HCC cells." (PMID 34976809, 2021). "Different works have shown that in vitro stimulation of tumor cell lines by soluble factors such as IL-1β, TNFα, IL-6 or TGFβ can enhance c-Met expression." (PMID 34771724, 2021). "The abnormal activation of the JAK–STAT pathway in cluster C promoted the production of some tumor-derived factors such as IL-6, TGF-β, VEGF, and other factors." (PMID 35070978, 2021). "Considering the bone metastases, interleukin (IL)-6, IL-8, IL-1β, and IL-11 mediate the crosstalk between bone cells and tumour cells acting on bone homeostasis: they show a bone trophic function and are regulators of bone remodelling." (PMID 34201209, 2021). "IL6 secretion has been identified to be the most characterized cytokine in PDAC, which is strongly associated with tumor survival." (PMID 34638560, 2021). "It has been proven that the excessive production of inflammatory cytokines such as IL-6 can increase the level of fibrinogen, which can mediate cellular interactions and influence tumor cell activities, including proliferation, migration, and apoptosis." (PMID 34234871, 2021). "CXCL1, like IL‐6, affects the invasion and migration of tumour cells and induces the recruitment of a variety of cytokines to form a tumour microenvironment that promotes the proliferation of tumour cells." (PMID 34216174, 2021). "The weak correlation between PD-L1 and IL-6 observed in the current study is further aligned with studies reporting that IL-6 can induce PD-L1 expression in tumor cells and immune cells." (PMID 35008176, 2021). "Growing evidence has shown that the release of molecules, such as IL-6, IL-10 and IL-34 by TAMs, contributed to the acquisition of a chemo/radioresistant phenotypes in tumor cells." (PMID 34830817, 2021). "It has also been suggested that IL-6 can be secreted by the tumour as a consequence of high circulating norepinephrine levels." (PMID 33715142, 2021). "The tumour infiltrating NK cells secrete pro-inflammatory cytokines such as IL-6 and activate various matrix metalloproteinases that facilitate tumour invasion." (PMID 34003341, 2021). "Depending on its localization in the tumor mass, IL-37 acts in different manners: high levels in peritumoral tissues, low levels in the tumor core, where it suppresses the production of IL-6 and β-catenin." (PMID 34944856, 2021). "The first signal controls IMCs production, mainly mediated by tumor-derived growth factors, such as IL-6, IL-11, IL-17A, G-CSF, GM-CSF, TNFα, and involves signal pathways including STAT3, IRF8, C/EBPβ, RB1, Notch, adenosine receptors A2b, NLRP3, and others." (PMID 34680276, 2021). "The current paradigm in inflammation and cytokine-induced ductal tumor development is IL-6 signaling promotes progression and metastasis." (PMID 34011405, 2021).
tumor (continued). "Irradiation promotes IL-6 production by the tumor microenvironment, which results in STAT3 phosphorylation and subsequent anti-inflammatory CCL2, CCL4, VEGF, and TGF-β cytokine production." (PMID 33800829, 2021). "Further, Ang1 expression was significantly lower among tumor samples with high IL-6 expression than in samples with low IL-6 expression (p = 0.021)." (PMID 33833265, 2021). "TNF-α, IL-6, IL-1, and chemokines induce tumor growth by promoting angiogenesis and suppressing immune-mediated tumor elimination, while dendritic cells (DCs) and natural killer (NK) cells play a critical role in the early defense against cancer." (PMID 34068653, 2021). "Any of the UPR sensors can trigger NF-κB-inducing, tumor-promoting, pro-inflammatory cascade implicated in macrophage activation and TNF-α, IL-6, IL-1β, and IL-8 cytokines production." (PMID 34671553, 2021). "Among these tumour hallmarks, the IL6-JAK-STAT3 pathway has been well-described to promote cancer progression as well as immunosuppression in an autocrine manner." (PMID 34374416, 2021). "Depletion of IL-6 in vivo resulted in inhibition of tumor growth and subsequent microglia infiltration." (PMID 34949203, 2021). "Considering tumor-associated endothelial cells (ECs) as a major source for IL-6 expression in GBM21, we utilized a tamoxifen-inducible, EC-specific gene-knockout system to precisely regulate IL-6 expression in the tumor microenvironment." (PMID 34103524, 2021). "IL-6 is involved in tumor–CAFs crosstalk, it can modulate the activation of fibroblasts, and, at the same time, support cancer cell growth." (PMID 34572947, 2021). "Blockade of IL6 in tumors co-cultured with fibroblasts resulted not only in the regression of tumor growth but also in the accumulation of CD8+ TILs in intratumoral tissues." (PMID 34960256, 2021). "The overactivation of KRAS signalling has been shown to enhance the secretion of interleukin-6 (IL-6), which is necessary for tumour initiation and progression and is important for the crosstalk between tumours and inflammation." (PMID 34776511, 2021). "Proinflammatory factors related to the tumor microenvironment include IL-6, IL-8, TNF-α, TNF-β, and FASL; the main relevant cytokines are IL-1, IL-2, IL-12, and IFN-γ." (PMID 34194957, 2021). "Similar to previous reports, high IL6 and IL8 values were associated with advanced tumor stage and impaired liver functions in our study." (PMID 34080071, 2021). "IL‐6, mainly produced by malignant tumor cells and activated immune cells, initiates cancer‐related inflammation and stem cell expansion in an autocrine manner." (PMID 34977871, 2021). "In conclusion, we found that raloxifene potently inhibits PDAC progression in vitro and in in vivo orthotopic tumor cell xenografts through a mechanism that involves binding and inhibition of gp130 and, thereby, abrogation of IL-6 signaling." (PMID 32940862, 2021). "CAFs regulate immunosuppressive tumor infiltrating lymphocyte (TIL) by affecting the secretion of interleukin-6 (IL-6) in the TME." (PMID 34284780, 2021). "Our further work identifies a role of CD40 for tumor resistance to anti-IL-6 and checkpoint blockade treatments." (PMID 34103524, 2021). "For the mechanisms, the exosomal contents and parathyroid Hormone-Related Protein (PTHrP) derived from tumor cells and IL-6 are found to promote WAT browning." (PMID 33413697, 2021). "This anti-tumor effect appeared to be mediated by the induction of pro-inflammatory cytokines like IL-6, TNF-α, and IFN-γ." (PMID 34177955, 2021). "IL-6 stimulates proliferation, promotes angiogenesis, and inhibits apoptosis of PCa cells and other tumor cells." (PMID 34357036, 2021). "Increasing evidence suggests that KRAS mutation preferentially induces an immunosuppressive TME by promoting the expression of immunomodulatory factors of tumour cells, such as transforming growth factor-β, interleukin-6, and interleukin-10203." (PMID 34776511, 2021).
tumor (continued). "The activation of Notch via tumor derived Jagged 1 induces the production of IL-6 by osteoblasts which has a positive effect on osteoclast differentiation and allows for the initiation of the vicious cycle of osteolysis and tumor development." (PMID 34503118, 2021). "Macrophages can contribute to tumor-promoting inflammation, e.g., by secretion of proinflammatory cytokines, like IL-6, IL-1β, TNFα." (PMID 33919517, 2021). "Co-injection with iBMSC significantly improved the metastasis ability of IMR32, which was demonstrated by the lower survival time and rate of mice, the higher tumor burden, lung weight, and IL6 expression in lung metastatic lesions." (PMID 34790130, 2021). "In the intestine, tumor-associated myeloid cells produce IL-23 which affect Th17 cell polarization and the subsequent production of the cytokines IL-17A, IL-21, TNF-α and IL-6 which in turn, provide the pro-tumorigenic inflammatory response in CRC." (PMID 32797354, 2021). "IL-17 induces the production of IL-6 by stromal and tumor cells, thus activating the STAT3 pathway, which favors the expression of inflammatory factors important for the regulation of leukocyte infiltration in inflammatory tissues." (PMID 34299314, 2021). "In breast tumors, the major sources of IL-6 are including tumor-derived fibroblasts, and tumor-infiltrated macrophages and lymphocytes." (PMID 33517609, 2021). "The release of tumor-derived factors, such as parathyroid hormone-related protein (PTHrP), interleukin 6 (IL-6), tumor necrosis factor (TNF), and transforming growth factor β (TGF-β), activates OC differentiation and bone-resorbing activity." (PMID 34830256, 2021). "IL6-induced upregulation of DNMT1 was also found to result in hypermethylation and silencing of genes linked to tumor suppression, adhesion, and apoptosis, including PAI-1, IL-4, Maspin, and IRF-7." (PMID 34901003, 2021). "For example, the interaction between hematologic tumor cells and stromal cells stimulates bone marrow stromal cells (BMSCs) to secrete IL-6 and granulocyte-macrophage colony-stimulating factor (GM-CSF), while MM tumor cells secrete IL-6 and VEGF, etc.." (PMID 34295898, 2021). "Overexpression of IL6 leads to the activation of Jak/Stat signaling, which promotes tumorigenesis and tumor progression." (PMID 34313788, 2021). "Following treatment with IL-6, CQ, and chemotherapy drugs, the tumor growth rate and tumor weight were measured to assess the role of IL-6-mediated autophagy in chemotherapy resistance." (PMID 34131122, 2021). "In this review, we, therefore, aimed to summarize available data on the IL-6 signaling pathway mechanisms and emphasize the IL-6 importance in the context of the tumor microenvironment." (PMID 34681685, 2021). "IL-6 concentrations are substantially increased in the tumor microenvironment, as it has pro-tumorigenic effects, increasing survival, growth, angiogenesis, and invasion." (PMID 33670492, 2021). "This transcription is responsible for the secretion of interleukins including: IL-1b, IL-6, and IL-8; Tumor Necrosis Factors: TNF-a, TNF-b; inducible cyclooxygenase (COX-2 favor prostaglandin synthesis); and inducible nitric oxide synthase (iNOS)." (PMID 34682182, 2021). "IL-6 activates Stat-3 signalling in regulator T cells and helps tumour cells escape immune surveillance." (PMID 34223877, 2021). "Blocking IL-6 signaling suppressed tumor formation and reduced STAT3 activation in Apcmin/+Ripk3-/- mice." (PMID 33996591, 2021). "MM derived exosomes also exaggerate osteolysis, driving the release of IL-6 (to promote tumour growth) and inhibiting OB differentiation via reduced Runx2, Osterix, and Osteocalcin." (PMID 34501423, 2021). "Tumor tissue showed a high amount of IFNγ, IL-6, and TNFα, which is consistent with a phenotype of TIL activation." (PMID 33986267, 2021).